ZNF722 (zinc finger protein 722)
Description:
May be involved in transcriptional regulation.
Synonyms: ZNF722P
Gene: Protein-coding gene on chromosome 7 (63,998,849 to 64,018,081, forward strand). Ensembl gene ENSG00000241149.
Subcellular location: Nucleus
Gene Ontology:
Molecular function: DNA-binding transcription factor activity, RNA polymerase II-specific; RNA polymerase II cis-regulatory region sequence-specific DNA binding
Biological process: regulation of DNA-templated transcription; regulation of transcription by RNA polymerase II
Cellular component: nucleus
Genetic constraint (gnomAD): Loss-of-function variants: 1 observed, 3.06 expected, observed/expected ratio (o/e) 0.33, 90% interval 0.11 to 1.45. That is too few expected variants to judge how well the gene tolerates losing a copy. Missense variants: 204 observed, 214.51 expected, observed/expected ratio (o/e) 0.95, 90% interval 0.85 to 1.07. Synonymous variants: 63 observed, 71.44 expected, observed/expected ratio (o/e) 0.88, 90% interval 0.72 to 1.09.
Homologues: Orthologues: chimpanzee ZNF722 (99% identical). Paralogues in human: ZNF735 (89% identical), ZNF679 (83% identical), ZNF716 (81% identical), ZNF708 (67% identical), ZNF254 (66% identical), ZNF728 (65% identical), ZNF726 (65% identical), ZNF506 (64% identical), ZNF486 (62% identical), ZNF90 (61% identical), ZNF492 (59% identical), ZNF676 (58% identical), and 164 more.